ACE (angiotensin I converting enzyme)
Diseases named in the same sentence as ACE in open-access papers (continued):
Sharing a sentence is not in itself a finding about the gene and the disease.
tuberculosis (52 papers, 2006 to 2026). A chronic, recurrent infection caused by the bacterium Mycobacterium tuberculosis. "We found Del/Del genotype of the ACE gene (rs4646994) showed significant association by setting up a protective factor for the development of tuberculosis." (PMID 35571459, 2022). "We also have explored the association between ACE polymorphisms and tuberculosis in the Amazonian Brazilian population, which is characterized by a genetic background of three parental populations (European, African, and Amerindians)." (PMID 35571459, 2022). "Interactions between the ACE I/D polymorphism and other risk factors can therefore influence the risk for tuberculosis disease." (PMID 35571459, 2022). "The results showed that ACE Del/Del genotype was associated with protection to tuberculosis development, in the domain model (OR = 0.465; p < 0.005)." (PMID 35571459, 2022). "The Del/Del genotype of the rs4646994 in ACE gene was associated with susceptibility to tuberculosis." (PMID 35571459, 2022). "In the present study, we aim to evaluate the association between ACE (Ins/Del) polymorphism and risk of tuberculosis in an admixture population such as the Brazilian population." (PMID 35571459, 2022). "Our case-control study suggests that the Del/Del genotype of the rs4646994 in ACE gene was associated with protective factors to tuberculosis." (PMID 35571459, 2022). "Laboratory investigations must include angiotensin converting enzyme (ACE) level and tuberculin intradermal reaction/Quantiferon test, considering the potential association of the disease with sarcoid or tuberculosis." (PMID 34524577, 2021). "The high concentration of serum angiotensin-converting enzyme (ACE) present in only 24–76 % of SA patients can also be present in tuberculosis and neoplasm, therefore, the diagnostic value is limited." (PMID 25194844, 2015). "Interestingly, the ACE polymorphism and tuberculosis protection in Amazon populations were significantly associated, however larger studies are necessary to deepen the relationship between the ACE gene and its potential protective factor for tuberculosis infection in the Amazonia population." (PMID 35571459, 2022). "Serum ACE levels may be elevated but lack specificity, as they may also be elevated in conditions such as tuberculosis or lymphoma." (PMID 41541976, 2025). "Variations in the Angiotensin-converting enzyme (ACE) may be one among many contributing factors for tuberculosis." (PMID 35571459, 2022). "However, increases of plasma ACE do not only occur in this disease, but also in other granulomatous illnesses such as tuberculosis, granulomatous hepatitis, leprosy, silicosis, and asbestosis and even in healthy persons." (PMID 24826302, 2013). "In addition, the ACE expression detected in human tuberculosis granulomas may reflect a functional equivalent ACE+ MΦ subset to the ACE+ granuloma MΦs that we report in this study." (PMID 36608122, 2023). "We report a rare case of non-articular osseous sarcoidosis with progressive pulmonary lesions and persistently normal inflammatory biomarkers (ACE, CRP, ESR, IL-2, and TNF-α) that required differentiation from metastatic bone tumors and tuberculosis." (PMID 40361953, 2025). "They collected blood samples from 40 male patients with tuberculosis before anti-tuberculosis chemotherapy was started and measured the serum levels of four tumour markers, including NSE, cancer antigen 125 (CA125), angiotensin-converting enzyme (ACE) and CYFRA21-1." (PMID 38822291, 2024). "In the tuberculosis group, ACE was measured in 30.2% of the patients (n = 19) and none of the patients had an elevated ACE level." (PMID 38787250, 2024). "However, serum ACE elevation is associated with activation of the monocyte-macrophage system and may be elevated in a variety of granulomatous and non-granulomatous conditions including ulcerative colitis, tuberculosis and alcoholic liver disease." (PMID 17335577, 2007).
tuberculosis (continued). "Laboratory tests confirmed elevated ACE levels, and tuberculosis was ruled out." (PMID 40106948, 2025). "Tuberculosis and angiotensin-converting enzyme (ACE) profiles were negative." (PMID 40666555, 2025). "Further laboratory evaluation included: a negative QuantiFERON tuberculosis (TB) test; negative heavy metal testing for arsenic, lead, and mercury; normal angiotensin-converting enzyme (ACE levels), negative celiac panel, and negative Helicobacter pylori serology." (PMID 29065902, 2017). "Serum calcium, angiotensin converting enzyme (ACE), lysozyme, alkaline phosphatase (ALP), Serum protein electrophoresis and interferon r release assay (IGRA) for tuberculosis were negative." (PMID 40729186, 2023).
left ventricular hypertrophy (50 papers, 2008 to 2026). Enlargement of the LEFT VENTRICLE of the heart. "Angiotensin converting enzyme (ACE) inhibitors were the only antihypertensive drugs associated with lower risk of left ventricular hypertrophy (OR: 0.08, 95% CI 0.03-0.19, p < 0.001)." (PMID 24444396, 2014). "In untreated hypertensive patients, the ACE D allele, with a 192% higher risk compared to homozygous II, behaved as a marker of left ventricular hypertrophy, a condition that may be opposed by antihypertensive treatment." (PMID 39591456, 2024). "Drugs like angiotensin-converting enzyme (ACE) inhibitors and beta-blockers are not only used for controlling left ventricular hypertrophy but also for sympathetic overactivity." (PMID 36000139, 2022). "ACE inhibition has been shown to improve arterial compliance and, by inhibiting angiotensin II formation, decrease left ventricular hypertrophy, generalized coagulability and possibly systemic sympathetic activity in diabetic and hypertensive patients." (PMID 33042111, 2020). "Inhibiting ACE has been shown to improve left ventricular hypertrophy (LVH) in patients and animals." (PMID 30382174, 2018). "In the literature, there are several studies evaluating the therapeutic benefits of ACE inhibitors or the intervention of AT1 antagonists in reducing left ventricular hypertrophy." (PMID 23383330, 2013). "Moreover, in hypertensive African Americans with left ventricular hypertrophy, ACE inhibitors increase anti-fibrotic biomarkers." (PMID 35656292, 2022). "There was significant difference in the prevalence of left ventricular hypertrophy (LVH) between ACE genotypes (II: 13.0 %; ID: 34.1 %; DD: 46.5 %; p value = 0.024) with an increased risk in carriers of the DD genotype (OR = 5.80; IC 95 % 1.50–22.44; p value = 0.011)." (PMID 26336879, 2015). "Left ventricular hypertrophy in hypertensive patients needs to be detected and assessed promptly to prognosticate these patients, address modifiable risk factors such as obesity, and blood pressure, and the initiation therapy that has been shown to reverse LVH such as ACE inhibitors." (PMID 40313582, 2025). "Polymorphisms including genes encoding components of the renin–angiotensin system (RAS), such as angiotensin-converting enzyme (ACE), have recently been shown to be associated with the risk of developing left ventricular hypertrophy (LVH) and thus may influence the clinical phenotype of HCM/DCM." (PMID 34750628, 2021). "There is a correlation between elevated levels of the cardiac renin-angiotensin system (RAS), which includes angiotensinogen, angiotensin-converting enzyme (ACE), angiotensin II, and left ventricular hypertrophy." (PMID 40463932, 2025). "Captopril, an angiotensin-converting enzyme (ACE) inhibitor, has been shown to be cardioprotective in the prevention and regression of left ventricular hypertrophy or attenuation of MI/R injury in both clinical and experimental settings." (PMID 26273143, 2015). "Studies have demonstrated that all components of RAS (e.g., renin, angiotensinogen, ACE and AngII receptors) are identified in the heart at both the mRNA and the protein levels and that RAS is activated in experimental left ventricular hypertrophy induced by hemodynamic overload." (PMID 25739102, 2015). "This is contrary to the fact that ACE inhibitors induce left ventricular hypertrophy regression, independent of changes in blood pressure." (PMID 24444396, 2014).
malaria (50 papers, 2005 to 2026). Malaria is a serious and sometimes fatal disease caused by a parasite that commonly infects a certain type of mosquito which feeds on humans. "Genetic factors such as angiotensin-converting enzyme (ACE) I/D polymorphism have been implicated in influencing malaria severity and outcomes." (PMID 42111647, 2026). "The first study to investigate the association of ACE insertion/deletion (I/D) within intron 16 with malaria found that the ACE I/D polymorphism, responsible for increased Ang II production, was significantly associated with mild malaria in India (p < 0.0001)." (PMID 37240057, 2023). "Regarding malaria, a study in India previously associated the D allele of ACE D/I polymorphism with malaria." (PMID 32625198, 2020). "This case aims to contribute to the debate about the role of ACE polymorphisms in malaria severity." (PMID 42111647, 2026). "This may suggest that people with hypertension associated with ACE2 (C→T) and ACE D/I polymorphisms are protected against malaria and COVID-19 too due to the reduced level of ACE2 expression." (PMID 36081516, 2022). "Although there is not sufficient evidence available to demonstrate it, the association of polymorphisms of the ACE and protection from severe malaria may also be the result of a natural selection process." (PMID 25232536, 2014). "Further evidence that ACE and ACE2 polymorphisms and consequent increased plasma levels of Ang II are associated with malaria severity was demonstrated in people with an African genetic background." (PMID 26779452, 2015). "A genetic association study was carried out in Orissa, India, to search for a possible influence of polymorphisms in angiotensin I-converting enzyme (ACE) and angiotensin II-converting enzyme (ACE2) on the outcome of malaria." (PMID 26779452, 2015). "A hypothesis suggests that genetic polymorphisms in the RAAS (e.g., ACE I/D, ACE2 rs2106809), that got selected for malaria protection, raise blood pressure, linking malaria exposure to increased hypertension risk." (PMID 39492784, 2024). "Lowered hepcidin levels could exacerbate iron metabolism issues in populations with cardiovascular disease, particularly, those residing in malaria-endemic areas and taking ACE inhibitors medication." (PMID 39885837, 2024). "The “indirect” hypothesis suggests that elevated blood pressure in populations living under chronic exposure to malaria may be due to specific genetic variations in the human RAS, such as insertion/deletion in ACE and cytosine/thymine substitution polymorphism." (PMID 39885837, 2024). "Alternative anti-hypertensive drugs, that do not target ACE, for hypertensive travelers would be decreasing the chances of developing CM in case of acquiring malaria." (PMID 25232536, 2014).
Cognitive impairment (47 papers, 2009 to 2025). Abnormal cognition is characterized by deficits in thinking, reasoning, or remembering. "Intriguingly, statistical and cluster analyses of longevity patients revealed trends towards higher frequency of cognitive impairment among affected individuals with damaging ACE mutations." (PMID 41009662, 2025). "A meta-analysis found that the use of drugs interacting with the RAS (both ACE inhibitors and ARAs) was significantly associated with a reduced risk of AD and aging-associated cognitive impairment." (PMID 36173067, 2024). "This study aimed to assess the pathogenetic roles of ACE and the genetic predisposition of its insertion/deletion (I/D) polymorphism in mild cognitive impairment (MCI) among T2DM patients." (PMID 28066203, 2016). "Moreover, clinical association analysis suggests a trend linking damaging ACE mutations with increased risk of cognitive impairment." (PMID 41009662, 2025). "The most widely studied of the mentioned genetic variants in the context of PD or cognitive impairment was the ACE I/D polymorphism which is responsible for a significant variance in ACE levels—the DD genotype results in two-fold higher plasma and tissue ACE levels than in the II carriers." (PMID 34302265, 2021). "The same effect was seen in a second study, where maternal protein deficiency during pregnancy induced hypomethylation of the promoter regions of RAAS-responsive genes, such as angiotensin converting enzyme (ACE), causing predisposition to HT in offspring as well as cognitive deficits." (PMID 27023534, 2016). "In addition, some studies found that AD patients have a higher frequency of the ACE gene D/D genotype, and the D-allele is associated with an increased serum ACE level, and predisposes to amnestic mild cognitive impairment." (PMID 23959119, 2013). "Anyway, enough scientific rationale already exists for undertaking systematic clinical trials in the prevention of cognitive impairment through the control of vascular risk factors and the use of statins, anti-inflammatory agents, ACE inhibitors, vitamins E and B12." (PMID 19895675, 2009). "Based on logistic regression analysis, the genotypes of ACE and the presence of alleles in ACE and AT2R1 genes were identified as prognostically significant factors in the development of cognitive impairments in the patients." (PMID 40283626, 2025). "This study identified the ACE and AT2R1 gene polymorphisms as important factors associated with cognitive impairment, with the D allele of the ACE gene and the C allele of the AT2R1 gene linked to reduced MOCA scores." (PMID 40283626, 2025). "CSF ACE levels were elevated in mild cognitive impairment (MCI) and AD cases and a positive correlation of cholesterol and 27-OH was found with RAS system actors in AD patients, linking cholesterol metabolism to brain RAS regulation." (PMID 34576302, 2021). "Oral administration of the centrally active ACE inhibitor perindopril prevented and improved cognitive impairment in AD mouse models via inhibition of brain ACE activity." (PMID 34576302, 2021). "It is likely that the benefit of ARBs and ACE inhibitors on cognitive impairment involves blood pressure lowering in addition to centrally mediated effects on inflammation, apoptosis and preservation of cerebral blood flow." (PMID 29543776, 2018). "Inhibition of ACE with centrally acting inhibitors such as perindopril reduced cognitive impairment in animal models of AD and VCI." (PMID 29543776, 2018). "Hyperactivation of AT1R activation and ACE signaling in astrocytes exacerbates cognitive impairment, cell death, inflammation, yet enhances BBB maintenance." (PMID 29543776, 2018). "Hyperactivation of AT1R and ACE signaling in neurons exacerbates cognitive impairment, cell death, and inflammation." (PMID 29543776, 2018).
Cognitive impairment (continued). "Hyperactivation of AT1R signaling and upregulation of ACE expression is well known for its role in vasoconstriction but within the brain, specifically exacerbates cognitive impairment, cell death and inflammation." (PMID 29543776, 2018). "Thus, the presence of risk alleles for both genes (D allele of the ACE gene and C allele of the AT2R1 gene) results in a 17.48% probability of developing cognitive impairments in studied patients." (PMID 40283626, 2025). "Thus, for patients with the D/D genotype of the ACE gene, the probability of developing cognitive impairments in chronic traumatic encephalopathy is 83.33%." (PMID 40283626, 2025). "Angiotensin-converting enzyme (ACE) has been shown to regulate brain function and inflammation, and studies using ACE inhibitors in mice have shown decreased type I interferon response and improved cognitive deficits, showing possible potential in the neuroprotective effects of ACE inhibitors." (PMID 38893713, 2024). "A higher ACE activity was found in the plasma of chronic schizophrenia patients, being positively correlated with plasma levels of the pro-inflammatory cytokines interferon gam (IFN-γ) and interleukin (IL)-17A, and associated with cognitive deficits." (PMID 36173067, 2024). "These neuroprotective functions may partially account for the improvement in cognitive deficits resulting from ACE inhibitor supplementation." (PMID 37630190, 2023). "Thus, the possible involvement of ACE in cognitive impairment and the effects exerted by ACE inhibitors seem to be far from being elucidated." (PMID 33802165, 2021). "Another ACE inhibitor that has been studied in cognitive impairment is ramipril." (PMID 29543776, 2018). "Since inflammation could be involved in the development of post-MI cognitive deficits the use beta-blockers or ACE inhibitors would be particularly relevant since they have anti-inflammatory properties." (PMID 30486235, 2018). "As predicted, significant differences were observed across neuropsychological test scores (e.g., MoCA‐B and ACE‐III), APOE ε4 positivity rates and AD PET imaging findings (Aβ and tau deposition) as cognitive impairment progressed (all p < 0.001)." (PMID 40717521, 2025). "Three intersecting targets—ACE, MAOA, and ADORA1—were identified as potential targets for caffeine in treating cognitive impairment under high‐altitude conditions, consistent with previous research." (PMID 39670604, 2024). "Several Aβ-degrading enzymes, including neprilysin (NEP), endothelin-converting enzyme (ECE), and angiotensin-converting enzyme (ACE) reduce Aβ levels and protect against cognitive impairment in mouse models of AD." (PMID 25309424, 2014). "Similarly, ACE inhibition can delay neurodegeneration via the retardation of tau hyperphosphorylation, while ACE2 and AGTR2 activation can protect against cognitive impairments." (PMID 37107585, 2023). "Our goal was to find out if there was a link between the actual concentration of ACE inhibitors and cognition in relatively young hypertensives without cognitive deficit and if there was a detectable difference between the two types of ACE inhibitors." (PMID 36361252, 2022). "Conversely, the same studies cited above reported that non-brain-penetrating ACE inhibitors enalapril and imidapril did not significantly affect Aβ-induced cognitive deficits." (PMID 34576302, 2021). "However, recent in vivo studies suggested that the amelioration of cognitive impairment achieved by perindopril, a centrally acting ACE inhibitor, was independent of its antihypertensive effect." (PMID 37630190, 2023). "In addition, we also confirmed that MKP, a tripeptide in CH-3 that has a strong ACE inhibitory effect with BBB penetration, showed a similar effect to CH-3 and thus may be one of the main players in the prevention of cognitive impairment by CH-3." (PMID 28158298, 2017).